TRPV4 (transient receptor potential cation channel subfamily V member 4)
Diseases named in the same sentence as TRPV4 in open-access papers (continued):
Sharing a sentence is not in itself a finding about the gene and the disease.
prostate adenocarcinoma (3 papers, 2019 to 2022). "A parallel investigation showed that TRPV4 was down-regulated in prostate adenocarcinoma-derived endothelial cells (A-TECs), thereby reducing their mechanosensitivity to extracellular matrix (ECM) rigidity." (PMID 36430727, 2022). "Conversely, TRPV4 was down-regulated in prostate adenocarcinoma-derived endothelial cells (A-TECs), which displayed enhanced motility due to their lower mechanosensitivity toward extracellular matrix (ECM) stiffness." (PMID 32038296, 2019). "In contrast, low TRPV4 expression was observed in only six cancer types, namely, adrenocortical carcinoma (ACC), kidney renal papillary cell carcinoma (KIRP), liver hepatocellular carcinoma (LIHC), prostate adenocarcinoma (PRAD), skin cutaneous melanoma (SKCM), and thyroid carcinoma (THCA)." (PMID 34262942, 2021).
prostate carcinoma (3 papers, 2018 to 2023). A carcinoma that arises from epithelial cells of the prostate gland. "Prostate cancer-derived endothelial cells with low TRPV4 expression showed increased migration and abnormal angiogenesis." (PMID 29772843, 2018).
renal fibrosis (3 papers, 2022 to 2025). A final common manifestation of a wide variety of chronic kidney diseases characterized by glomerulosclerosis and tubulointerstitial fibrosis. "The underlying mechanism between TRPV4 and renal fibrosis still needs further elaboration." (PMID 36277193, 2022). "It is clear that controlling TRPV4 and lactate is an effective way for hypertensive phenotypes to inhibit renal fibrosis." (PMID 36160854, 2022). "TRPV4 knockdown abolished this beneficial effect of hypertension-induced renal fibrosis." (PMID 36277193, 2022).
retinal detachment (3 papers, 2021 to 2024). An eye emergency condition which may lead to blindness if left untreated. "Furthermore, osmolarity-activated TRPV4 increases the production of IL-1β and IL-6 in intervertebral disc cells; during acute retinal detachment-induced swelling of Müller cells, TRPV4 activation led to MCP-1 release and photoreceptor death." (PMID 34789280, 2021). "Thus, TRPV4 inhibitors could suppress photoreceptor death in retinal detachment, and targeting TRPV4 in Müller glial might represent a novel therapeutic target for the prevention of photoreceptor cell death after retinal detachment." (PMID 39578735, 2024). "In the case of acute retinal detachment, the number of apoptotic photoreceptors was reduced by approximately 50% in TRPV4 knockout mice relative to wild-type mice, which may be attributable to TRPV4 in photoreceptors more than that expressed in retinal pigment epithelium (RPEs)." (PMID 38903773, 2024).
scoliosis (3 papers, 2015 to 2025). A congenital or acquired spinal deformity characterized by lateral curvature of the spine. "The present patient presented with reduced muscle strength in the distal extremities, which is inconsistent with spinal cord compression in scoliosis, suggesting that this TRPV4 mutation may result in a mixed phenotype of severe skeletal dysplasia and neuromuscular pathology with motor inability." (PMID 40258774, 2025). "Two missense mutations of TRPV4 (R616Q and V6201) lead to gain-of-function mutation of TRPV4, which significantly increases the open probability of TRPV4 channel, resulting in the development of bone metabolic disorders like scoliosis." (PMID 40078961, 2025).
Sensory neuropathy (3 papers, 2015 to 2022). Peripheral neuropathy affecting the sensory nerves. "Mutations in TRPV4 cause CMT2C, a hereditary motor and sensory neuropathy with diaphragm and vocal cord paresis." (PMID 28553203, 2017).
skin cutaneous melanoma (3 papers, 2021 to 2024). "Among multiple cancers, skin cutaneous melanoma possesses a higher abundance of TRPV4, and in this type of cancer, the acquired results indicated that TRPV4 promotes metastasis through cell motility regulation." (PMID 38730655, 2024). "To investigate the expression profile of TRPV4 in different cancers, we analyzed The Cancer Genome Atlas (TCGA) datasets and acquired results indicating that Skin Cutaneous Melanoma (SKCM) possesses a higher abundance of TRPV4 among multiple cancers." (PMID 36499486, 2022).
Ventriculomegaly (3 papers, 2020 to 2022). An increase in size of the ventricular system of the brain. "Intraventricular administration of LPA caused elevated brain water content and ventriculomegaly in experimental rats, via its action as an agonist of the choroidal transient receptor potential vanilloid 4 (TRPV4) channel." (PMID 36068581, 2022). "Activation of TRPV4 causes the NKCC1 hyperactivity underlying the TRPV4-mediated elevated CSF secretion rate seemingly contributing to the ensuing ventriculomegaly signifying PHH." (PMID 36068581, 2022). "Here, we demonstrate an additional acute (24 h) effect of intraventricularly-delivered LPA causing ventriculomegaly and elevated brain fluid content in adult rats by its ability to act as an agonist of the TRPV4 channel." (PMID 36068581, 2022). "In the current studies, we show that — in the homozygous, hydrocephalic animals — treatment with TRPV4 antagonists alleviates the development of ventriculomegaly." (PMID 32938829, 2020). "It was proposed that TRPV4 acts as an important signaling hub protein in the luminal membrane of the choroid plexus where it can acutely respond to insult and may be activated in response to ventriculomegaly." (PMID 36050779, 2022). "Here, we demonstrate that LPA is indeed elevated in patients with subarachnoid haemorrhage (SAH) and in an animal model of IVH and reveal its ability to directly modulate the ion channel TRPV4, which subsequently promotes NKCC1-mediated CSF hypersecretion and ventriculomegaly." (PMID 36068581, 2022).
acute lung injury (2 papers, 2015 to 2024). A condition of lung damage that is characterized by bilateral pulmonary infiltrates (pulmonary edema) rich in neutrophils, and in the absence of clinical heart failure. "Transient receptor potential vanilloid 4 (TRPV4), a calcium-permeable mechanoreceptor channel has been shown to be a major determinant of ventilator-induced acute lung injury in adult models." (PMID 26006045, 2015). "TRPV4 channels control epithelial and endothelial barrier integrity in response to stretch or increased vascular pressure and are a major determinant of ventilator-induced acute lung injury." (PMID 26006045, 2015).
acute pancreatitis (2 papers, 2016 to 2022). An acute inflammatory process that leads to necrosis of the pancreatic parenchyma. "Furthermore, our novel dual-channel blocker inhibited inflammation and pain-associated behavior in a model of acute pancreatitis – known to also rely on TRPV4 and TRPA1." (PMID 27247148, 2016). "In the acinar cells of patients with acute pancreatitis, the Piezo1 of the acinar cells is upregulated and induced PLA2 to activate the TRPV4 channel to cause the continuous increase of Ca2+ and damage the mitochondrial function." (PMID 35154133, 2022).
allergic contact dermatitis (2 papers, 2023 to 2024). An inflammatory skin condition caused by an immune response to direct contact between the skin and an allergen. "Previous studies showed a correlation between TRPV4 and itch behavior in both SADBE and dinitrofluorobenzene induced allergic contact dermatitis." (PMID 38347451, 2024).
autism (2 papers, 2022 to 2025). Persistent deficits in social interaction and communication and interaction as well as a markedly restricted repertoire of activity and interest as well as repetitive patterns of behavior. "It was reported that whole-genome sequencing of 85 quartet families (two parents and two ASD-affected children) with autism revealed the occurrence of frame-shift mutations in the TRPV4 gene among the autism patients." (PMID 39333347, 2025). "Collectively, our data highlight the NAc Trpv4 alterations as a potentially common and unifying molecular underlying factor in sociability and aberrant intrinsic neuronal properties in Shank3 mouse models for autism." (PMID 35022531, 2022). "Recently, studies have turned to the TRPV4 channel as a potential player in the pathophysiology of autism." (PMID 39333347, 2025). "To date, no instances of TRPV4 mutations directly linked to autism have been reported, underscoring the need for further investigation into its role in the disorder’s pathogenesis." (PMID 39333347, 2025). "Studies utilizing animal models have underscored the significance of TRPV4 in fundamental processes such as neuronal development, synaptic plasticity, and neurotransmitter release, all of which are mechanisms potentially dysregulated in autism." (PMID 39333347, 2025). "Our data not only suggest that activation of the immune system may unmask autism-related behavioral phenotypes in genetically vulnerable mice but also ascribe Trpv4 as a potential therapeutic target for sociability defects in Autism." (PMID 35022531, 2022).
basal cell carcinoma (2 papers, 2021 to 2025). A carcinoma involving the basal cells. "Similarly, RhoA/ROCK is controlled by the TRPV4 channel and the activation of RhoA/ROCK has been shown to regulate downstream signaling transcription factors including Stat3 and Gli1 in amoeboid cancer cells and basal cell carcinomas, respectively." (PMID 40682198, 2025).
Bladder (2 papers, 2014 to 2020). "In contrast, TECs from a transgenic adenocarcinoma mouse prostate model exhibited low levels of TRPV4 expression compared to normal endothelial cells." (PMID 32843668, 2020).
bone cancer (2 papers, 2023 to 2024). A primary or metastatic malignant neoplasm affecting the bone or articular cartilage. "We found that the TRPV4 inhibitor (HC067047) significantly relieved bone cancer pain, which causes overexpression of TET1 and TRPV4, and that inhibition of TET1 reduces TRPV4 expression." (PMID 37190609, 2023). "The boosted expression of TRPA1-, TRPV1-, and TRPV4-immunoreactive cells in ipsilateral L4–5 DRG due to bone cancer proliferation was inhibited by LTTL gel application." (PMID 38730655, 2024). "We found that TET1 expression was increased in BCP rats, and the TET1 inhibitor relieved bone cancer pain and decreased TRPV4 expression." (PMID 37190609, 2023). "According to qPCR results, TET1 and TRPV4 mRNA levels gradually increased after the onset of bone cancer pain compared to those in the sham group, but TET2 mRNA levels remained constant over time." (PMID 37190609, 2023). "As far as we know, this study was the first to show that TET1 inhibition downregulated TRPV4 expression and alleviated bone cancer pain in rats." (PMID 37190609, 2023). "In summary, the study suggests that TET1 contributes to bone cancer pain by upregulating TRPV4 expression in the L4–6 DRG of rats." (PMID 37190609, 2023). "In another study focusing on CIBP, researchers sought to investigate whether a demethylase named TET1, previously discovered to be overexpressed in the DRG of female rats with bone cancer pain, also contributed to the upregulation of TRPV4 expression." (PMID 38730655, 2024). "Therefore, we examined the expression changes of TRPV4 after intrathecal administration of TET1 inhibitors to rats with bone cancer pain." (PMID 37190609, 2023). "In this study, we hypothesized that TET1, a demethylase elevated in the DRG of rats with bone cancer pain, upregulates TRPV4 expression." (PMID 37190609, 2023). "To verify whether TET1 or TRPV4 regulates bone cancer pain, we respectively injected the TET1 inhibitor Bobcat339 and TRPV4 inhibitor HC067047 intrathecally into BCP rats." (PMID 37190609, 2023). "Similarly to this, TRPV4 inhibition significantly reduced the abnormal pain experienced by rats with bone cancer pain." (PMID 37190609, 2023). "Therefore, we suggested that TET1 may contribute to bone cancer pain by upregulating TRPV4 expression in BCP rats." (PMID 37190609, 2023). "As a result, these findings suggested that TET1 may contribute to bone cancer pain by upregulating TRPV4 expression in the L4–6 DRG of BCP rats and that TET1 or TRPV4 may become therapeutic targets for bone cancer pain." (PMID 37190609, 2023).
breast invasive carcinoma (2 papers, 2021 to 2022). "For paired tumors and normal tissues in TCGA, TRPV4 was overexpressed in BLCA, CESC, CHOL, COAD, ESCA, LUSC, pheochromocytoma/paraganglioma (PCPG), and STAD, while low TRPV4 expression was observed in LIHC, PRAD, breast invasive carcinoma (BRCA), kidney chromophobe (KICH), and KIRP." (PMID 34262942, 2021).
bronchitis (2 papers, 2017 to 2020). An acute or chronic inflammatory process affecting the bronchi. "This study delineates a novel mast cell–ASM interaction and TRPV4 as a driver of IgE-independent mast cell-dependent bronchospasm." (PMID 32299856, 2020). "The objective of the present study was to investigate a role for IgE-independent, mast cell–ASM interaction in TRPV4-induced bronchospasm." (PMID 32299856, 2020).
chondrodysplasia (2 papers, 2021 to 2025). "Additionally, for TRPV4 mutation-induced OA chondrodysplasia, the TRPV4 activators GSK1016790A or 4α-PDD have shown therapeutic efficacy." (PMID 40376614, 2025). "TRPV4 is a positive regulator of SOX9 and mutations in this gene are linked to chondrodysplasia." (PMID 34663442, 2021).
Cognitive impairment (2 papers, 2025 to 2026). Abnormal cognition is characterized by deficits in thinking, reasoning, or remembering. "Therefore, TRPV4 hyperactivation caused hippocampal neuronal death, which led to cognitive impairment in aging." (PMID 41341920, 2025). "In a lipopolysaccharide-induced systemic inflammation model, TRPV4 hyperactivation promoted hippocampal inflammation and pyroptosis, resulting in cognitive impairment." (PMID 41341920, 2025).
gout (2 papers, 2023 to 2024). A condition characterized by painful swelling of the joints, which is caused by deposition of urate crystals. "One recent study also highlights an important role of macrophage TRPV4’s involvement in gout pain and inflammation." (PMID 38627393, 2024). "Specific deleting TRPV4 expression in macrophages results in attenuated pain response and inflammation in gout model mice." (PMID 37464384, 2023).
invasive ductal carcinoma (2 papers, 2017 to 2024). "Analysis of 761 samples revealed that TRPV4 expression is significantly different between normal, invasive ductal carcinoma (IDC) and metastatic (Mets) lesions." (PMID 28530703, 2017).
Lowe syndrome (2 papers, 2017 to 2024). "Studies on Lowe syndrome have suggested that OCRL may act through regulation of TRPV4, and a novel disease-causing OCRL allele prevents TRPV4-mediated calcium signaling." (PMID 38903773, 2024). "However, different studies have shown the opposite effect on IOP after TRPV4 activation in Lowe syndrome patients." (PMID 28368307, 2017).
lymph node metastasis (2 papers, 2023). "TRPV4 expression has been associated with early lymph node metastasis and poor overall survival." (PMID 37240443, 2023). "TRPV4 has also shown promise in diagnostics, playing an important role in predicting early lymph node metastasis and poor OS in gastric and ovarian adenocarcinoma." (PMID 38188686, 2023).
Myocardial fibrosis (2 papers, 2024 to 2025). "Therefore, the pharmacological blockade of TRPV4 represents a promising strategy to therapeutically interfere with myocardial fibrosis and fibrosis-associated cardiac disorders." (PMID 40149710, 2025). "Since the activation of TRPV4 channels has also been associated with cardiac fibrosis, the potential therapeutic benefits of TRPV4 channel inhibition to attenuate calcium overloading and myocardial fibrosis warrant future study." (PMID 39204134, 2024). "Emerging evidence suggests that TRPV1, TRPV3, and TRPV4 channels play a crucial role in myocardial fibrosis." (PMID 40149710, 2025).
non-melanoma skin carcinoma (2 papers, 2018 to 2022). "IL-8 secretion in human non-melanoma skin cancer can be stimulated by TRPV4, thereby leading to a possibly inhibitory autocrine circuitry, because IL-8 induces the downregulation of TRPV4 channels." (PMID 29772843, 2018).
oral cancer (2 papers, 2025). "Trpv4 was more highly expressed than transient receptor potential cation channel subfamily A member 1 (Trpa1) and transient receptor potential cation channel subfamily V member 1 (Trpv1), channels associated with oral cancer pain in neurons." (PMID 40144515, 2025). "We demonstrate that activation of TRPV4 (on Schwann cells) mediates mechanical sensitivity and oral cancer pain." (PMID 40144515, 2025). "We found that antagonism of TRPV4 reduced mechanical hypersensitivity in oral cancer pain models and that conditioned media (CM) from TRPV4-activated Schwann cells induced hypersensitivity to mechanical stimulation." (PMID 40144515, 2025). "In conclusion, our study identifies activation of TRPV4 in Schwann cells as a potential mediator of mechanically induced pain suffered by oral cancer patients." (PMID 40144515, 2025). "The role of mechanosensitive ion channels in oral cancer pain, such as TRPV4, is not fully understood." (PMID 40144515, 2025). "We examined the impact of TRPV4 inhibition on oral cancer pain in NU/J and C57BL/6J mice injected with human tongue cancer cell line (HSC-3) and mouse oral cancer cell line (MOC2) in the hind paw or tongue." (PMID 40144515, 2025). "Our objective was to investigate the role of Schwann cell TRPV4 in oral cancer pain." (PMID 40144515, 2025). "TRPV4 activation plays a role in mediating mechanically induced pain of oral cancer." (PMID 40144515, 2025). "Thus, TRPV4 on Schwann cells is likely to play a greater role in mediating oral cancer pain than TRPV4 on neurons." (PMID 40144515, 2025). "We hypothesized that TRPV4, a mechanosensitive ion channel, mediates oral cancer mechanical nociception." (PMID 40144515, 2025). "To examine the involvement of TRPV4 in oral cancer-related pain, we investigated whether antagonism of TRPV4 would reduce mechanical allodynia and thermal hyperalgesia evoked by the growth of oral cancer cells in the mouse hind paw." (PMID 40144515, 2025). "Here, we investigated whether TRPV4 is involved in oral cancer pain." (PMID 40144515, 2025). "Subsequently, we administered vehicle or different doses of a highly selective TRPV4 antagonist, GSK2193874 (2.5, 25, and 250 μg), into the cancer model, and measured the effect on oral cancer-induced mechanical allodynia and thermal hypersensitivity." (PMID 40144515, 2025). "Although we have not determined the specific nociceptive mediators released by Schwann cells following TRPV4 activation, previous studies suggest the involvement of IL-6, CX3CL1, and TNF-α from Schwann cells in oral cancer pain." (PMID 40144515, 2025). "Thermal hypersensitivity in our HSC-3 oral cancer model was not reversed by the antagonism of TRPV4." (PMID 40144515, 2025).
oral squamous cell carcinoma (2 papers, 2021 to 2022). "In this study, we combined the use of an anticancer drug, cisplatin, with a TRPV4 agonist and examined their effect on an animal model of oral squamous cell carcinoma." (PMID 36143906, 2022).
osteonecrosis (2 papers, 2019 to 2020). A none disease characterized by death of bone tissue due to a lack of blood supply. "Exomic capture allowed us to find a possible cause for P24’s osteonecrosis since this patient harbored a homozygous TRPV4 variation." (PMID 32641076, 2020). "TRPV4 mutations have been found in skeletal dysplasia, arthropathies and in a familial form of osteonecrosis." (PMID 32641076, 2020). "Recently, a novel gain of function TRPV4 variant was associated with inherited osteonecrosis of the femoral head." (PMID 31248428, 2019). "Thanks to exomic capture, we reorientated initial diagnosis for P35 (probable myeloproliferative syndrome) and explained a part of the phenotype in P24 (osteonecrosis and TRPV4), P26 (HAMP and iron overload) and P35 (painful crisis and SCN9A)." (PMID 32641076, 2020). "The TRPV4 mutation could explain osteonecrosis but not hemolysis." (PMID 32641076, 2020).